FUNDC1 (FUN14 domain containing 1)
Diseases named in the same sentence as FUNDC1 in open-access papers (continued):
Sharing a sentence is not in itself a finding about the gene and the disease.
cancer (continued). "We determined whether FUNDC1 expression was correlated with the immune infiltration level in different cancers by calculating the coefficient of FUNDC1 expression and immune infiltration level in 39 cancer types in TIMER." (PMID 31998650, 2019). "In this study, we demonstrated the prognostic value of FUNDC1 in pan-cancer." (PMID 31998650, 2019). "Future prospective studies focusing on FUNDC1 expression and immune infiltration in a cancer population could help provide a definitive answer." (PMID 31998650, 2019). "Next, we investigated the prognostic value of FUNDC1 for pan-cancer in different databases." (PMID 31998650, 2019). "Taken together, these findings suggest that FUNDC1 plays an important role in the recruitment and regulation of immune infiltrating cells in cancers, which may eventually influence patient survival." (PMID 31998650, 2019). "Furthermore, our study suggests that FUNDC1 has potential oncogene characteristics, and inhibition of FUNDC1 promotes the sensitivity of cancer cells to chemoradiotherapy." (PMID 28719148, 2017). "Interestingly, FUNDC1 showed a protective effect on pan-cancer, except LIHC." (PMID 35448958, 2022). "Hence, this study provides insights into the use of the mitophagy regulator FUNDC1 as a prognostic marker in pan-cancer from an immuno-oncological perspective, which could benefit future mechanistic studies and aid in the development of immunotherapies." (PMID 31998650, 2019). "Meanwhile, the role of FUNDC1 might be context dependent and could vary among different cancers." (PMID 31998650, 2019). "Interestingly, this high FUNDC1 expression was negatively correlated with tumor progression and patient prognosis whereas reduction of FUNDC1 levels halted cancer cell proliferation and in parallel induced apoptosis as well as sensitivity to both cisplatin and ionizing irradiation." (PMID 30250843, 2018). "Dysregulation of mitophagy-related proteins, such as FUNDC1, Parkin, BNIP3, BNIP3L/NIX, and p62/SQSTM1, has been shown to be correlated with cancer." (PMID 39524226, 2024). "Thus, it remains unclear whether FUNDC1 can be characterized as a friend or foe in pan-cancer." (PMID 31998650, 2019). "However, the roles of FUNDC1 in human cancer biology remain unknown." (PMID 28719148, 2017). "Moreover, like other well-known mitophagy receptors such as BNIP3L and FUNDC1, CLU overexpression triggers mitophagy to clear damaged mitochondria, protecting cancer cells from cisplatin-induced stress." (PMID 38447939, 2024). "The sustained intracellular Ca2+ levels in cancer cells can activate the AMPK-ULK1 phosphorylation and FUNDC1 signaling during hypoxia for mitophagy, highlights the significance of calcium-mitophagy coordination in regulating the cell proliferation during various stress conditions." (PMID 36927870, 2023). "For patient prognosis, analysis of FUNDC1 in Kaplan-Meier Plotter and GEPIA revealed that increased FUNDC1 expression correlated with a favorable prognosis in LUSC as well as an overall beneficial effect on cancers." (PMID 31998650, 2019). "Toward this direction, both FUNDC1 and PGAM5 are only expressed in NSCLC epithelial cells and the adjacent macrophages which through yet unknown mechanisms sent signals to neighboring cancer cells, thus determining their fate." (PMID 30250843, 2018). "However, unlike in non-cancerous diseases, the role of FUNDC1 in pan-cancer has been largely underexplored." (PMID 31998650, 2019). "Fifth, despite the finding that FUNDC1 expression correlates with both immune cell infiltration and patient survival in cancers, we could not prove that FUNDC1 affects patient survival through immune infiltration." (PMID 31998650, 2019). "Furthermore, FUNDC1 expression was also significantly correlated with the infiltration levels of B cells, CD8+ T cells, CD4+ T cells, macrophages, neutrophils, and dendritic cells in 10, 20, 16, 16, 19, and 19 cancer types, respectively." (PMID 31998650, 2019).
tumor (31 papers, 2017 to 2025). "The enhanced migration and invasion resulting from reduced FUNDC1 expression is linked to increased liver metastasis in vivo but is also accompanied by decreased tumor cell proliferation." (PMID 39430236, 2024). "To investigate the potential immunomodulatory role of FUNDC1 in the tumor microenvironment, we explored the association between FUNDC1 expression and the tumor-infiltrating immune cells in TCGA cohorts." (PMID 39668821, 2024). "Solidifying the importance of FUNDC1 control on mitochondrial dynamics on metastatic phenotypes, increases in tumor cell invasion by loss of FUNDC1 required DRP1." (PMID 35356277, 2022). "In contrast, FUNDC1 deficiency inhibited angiogenesis that reduced tumor size significantly in mice." (PMID 35011599, 2021). "Many studies reported that mitophagy-associated molecules PINK1, Parkin, BNIP3, FUNDC1 promote tumor development, and provide targets for therapeutic inhibition in multiple cancers." (PMID 32587855, 2020). "Similar to previous studies, immune infiltration analysis in our study indicates that FUNDC1 expression is associated with the infiltration of tumor-infiltrating lymphocytes, MDSCs, NK cells, pDC cells, and neutrophils in EC, suggesting the important roles of FUNDC1 in tumor immunology." (PMID 39668821, 2024). "Taken together this suggests that loss of FUNDC1 results in misfolding and subsequent decreased complex V activity, increasing mitochondrial ROS, which drives crucial changes in mitochondrial dynamics to facilitate tumor cell migration and invasion." (PMID 35356277, 2022). "Notably, the results suggested that FUNDC1 correlates with tumor-associated macrophage infiltration in LIHC and LUSC." (PMID 31998650, 2019). "Furthermore, markers of infiltrating immune cells, such as tumor-associated-macrophages (TAMs), exhibited different FUNDC1-related immune infiltration patterns." (PMID 31998650, 2019). "Under stress conditions such as chemotherapy and radiotherapy, tumor cells can activate mitophagy through pathways such as PINK1/Parkin, BNIP3, or FUNDC1 to counteract the damage caused by drugs and radiation, leading to the development of resistance." (PMID 41551160, 2025). "While recent studies have shown that the expression of FUNDC1 in cervical cancer cells was significantly increased and its depletion leads to inhibiting the tumor cells’ proliferation and increases cell sensitivity to chemotherapy and ionizing radiation." (PMID 40943612, 2025). "Silencing FUN14 domain-containing 1 (FUNDC1) inhibits tumor angiogenesis by decreasing the formation of MAMs." (PMID 41573684, 2025). "FUNDC1 was predominantly located in the cytoplasm of tumor cells, and HIF-1α was detected in the cytoplasm and nucleus." (PMID 39668821, 2024). "The oncogenic Src kinase-dependent regulatory mechanism for FUNDC1-LC3 interaction also indicates that FUNDC1-dependent mitophagy plays a role in Src-driven tumor cell migration and invasion." (PMID 39201332, 2024). "Under the hypoxic condition, mitophagy receptor FUNDC1 accumulates at the mitochondria-associated membranes to stabilize the FUNDC1/ULK1 complex for cell survival and tumor development." (PMID 39035027, 2024). "We investigated the potential role of FUNDC1 in EC progression and chemoresistance, based on tumor specimen analyses and in vitro experiments." (PMID 39668821, 2024). "PINK1, Parkin, BNIP3, NIX, and FUNDC1 have been reported to facilitate tumor progression and recurrence." (PMID 36207761, 2022). "Understanding the role of various components such as Pink1/Parkin, BNIP3, FUN14 domain-containing protein 1 (FUNDC1), optineurin (OPTN), microtubule-associated protein 1A/1B-light chain 3 (LC3), etc. in mitophagy will help in managing tumor progression." (PMID 36365094, 2022). "Here, it was found that ablation of FUNDC1 in prostate cancer cells reduced primary tumor growth and increased metastasis to the lung and liver in vivo." (PMID 35356277, 2022).
tumor (continued). "More recently a role for mitochondrial protein FUN14 Domain Containing 1 (FUNDC1), traditionally studied as a mitophagy receptor, in controlling tumor metastasis through controlling mitochondrial dynamics was explored." (PMID 35356277, 2022). "In general, FUNDC1 expression was higher in tumor and identified as a detrimental prognostic factor in LIHC." (PMID 35448958, 2022). "In the early stage of tumorigenesis, mitophagy maintains normal cell metabolism and inhibits tumorigenesis, while in the later stage of tumor development, the occurrence of FUNDC1 mitophagy improves cell tolerance and promotes the development of the tumor." (PMID 35011599, 2021). "To further confirm the function of FUNDC1 in vivo, we established mouse xenograft models and found that FUNDC1 knockdown significantly suppressed tumor growth and lung metastasis." (PMID 34272359, 2021). "The mouse xenograft experiments showed that the suppression of tumor growth and lung metastasis induced by FUNDC1 knockdown was also reversed by miR-101 suppression." (PMID 34272359, 2021). "In TIMER, after adjustments for tumor purity, the FUNDC1 expression level was significantly correlated with 30 out of 45 immune cell markers in LIHC and 19 out of 45 immune cell markers in LUSC." (PMID 31998650, 2019). "The median follow‐up period was 38 months for all patients, and 11 patients died of tumor‐related complications during this period (27.3% were low FUNDC1 expression and 72.7% were high FUNDC1 expression)." (PMID 28719148, 2017). "Depletion of FUNDC1 significantly inhibited the proliferation of tumor cells, induced apoptosis, and enhanced cell sensitivity to cisplatin and ionizing radiation (IR)." (PMID 28719148, 2017). "Among the 82 tumor tissue specimens, 45 cases (54.9%) had high FUNDC1 protein expression (score: > 8)." (PMID 28719148, 2017). "The FUNDC1–LonP1 axis regulates multiple tumor cell plasticity by mitochondrial reprogramming." (PMID 36831455, 2023). "PGAM5 dissociated from BCL-xL could control mitochondrial fission, mitophagy, and tumor cell apoptosis through FUNDC1 pathway." (PMID 36157211, 2022). "Furthermore, in the LLC-derived tumor model, ectopic VEGFR2 expression antagonized the decreased CD31-positive vessel density occurring with FUNDC1 deficiency, thus enhancing tumor growth and reversing the reduced tumor size." (PMID 33972548, 2021). "Moreover, the deletion of FUNDC1 in tumor cells obviously inhibited cell proliferation, triggered cell apoptosis and increased the sensibility of tumor cell to chemo-radiotherapy such as cisplatin and ionizing radiation." (PMID 32587855, 2020). "Therefore, it is reasonable to surmise that immune infiltration can interact with FUNDC1-mediated activities in both immune cells and tumor cells." (PMID 31998650, 2019). "In addition, the FUNDC1 expression level in LIHC had no relation with tumor purity (R = −0.086, P = 0.112), while the FUNDC1 expression level in LUSC was positively correlated with tumor purity (R = 0.12, P = 8.55E-03)." (PMID 31998650, 2019). "We did find significant correlations between tumor FUNDC1 expression and immune cell infiltration, even though a cause-effect relationship could not be established in the current study." (PMID 31998650, 2019). "However, in LUSC, the FUNDC1 expression level had a significant positive correlation with tumor purity, indicating its comparative enrichment in tumor cells." (PMID 31998650, 2019). "Such difference may be attributable to the different enrichment patterns of FUNDC1 in the tumor microenvironment." (PMID 31998650, 2019). "Therefore, we further analyzed the correlations of FUNDC1 expression and B cell/macrophage markers in tumor tissues of LIHC and LUSC in GEPIA." (PMID 31998650, 2019).
tumor (continued). "In addition, immune cell infiltration analysis by Tumor Immune Estimation Resources (TIMER) database and the Xiantao academic tool demonstrated that FUNDC1 expression was strongly associated with the infiltration of Th2, NK, Th17, Tem, pDC, neutrophil, MDSC, CD4+ T, and γδ T cells." (PMID 39668821, 2024). "Overall, the role of FUNDC1-mediated mitophagy may differ in different stages of tumor development." (PMID 35011599, 2021). "These interactions between tumor cells and infiltrating immune cells help explain the findings from this study indicating that TAMs have a positive correlation with FUNDC1 expression in LIHC and that the high expression of FUNDC1 is associated with a worse LIHC patient prognosis." (PMID 31998650, 2019). "Thus, it is reasonable to surmise that FUNDC1 expression may influence patient survival through tumor cell proliferation." (PMID 31998650, 2019). "For infiltrating TAMs, after adjustment for tumor purity, in LIHC, FUNDC1 was positively correlated with CD80 and CD86, and in LUSC, FUNDC1 negatively correlated with CD80, indicating the constitutive effect of TAMs on differences in tumor cell survival." (PMID 31998650, 2019). "Additionally, while we validated the feature genes and confirmed our research findings, only three genes' expressions (CSNK2A1, FUNDC1, and SRC) in tumor cells supported our results." (PMID 38155968, 2023). "Moreover, tumor cells may evade immune recognition by upregulating mitophagy receptors such as BNIP3 and FUNDC1, leading to a state of immune tolerance." (PMID 41551160, 2025). "Moreover, blocking FUNDC1-related MAM formation with a cell-penetrating inhibitory peptide significantly suppresses the expressions of downstream angiogenic genes and inhibits tumor angiogenesis." (PMID 33972548, 2021). "Besides, FUNDC1 expression is not related with the tumor purity in LIHC, while it does have significant positive correlation with the tumor purity in LUSC." (PMID 31998650, 2019). "However, the role of FUNDC1 in other important aspects like tumor metastasis has not been thoroughly studied." (PMID 31998650, 2019). "Furthermore, several studies have reported that FUNDC1 suppresses HCC initiation by blocking inflammatory responses in hepatocytes, whereas upregulation of FUNDC1 expression at the late stage of tumor development may promote tumor growth." (PMID 35154486, 2022). "However, according to our study, FUNDC1 is an unfavorable prognostic factor for LIHC patients, though the situation may vary according to different characteristics such as gender, race, alcohol consumption, hepatitis infection, tumor grade, tumor stage, or vascular invasion." (PMID 31998650, 2019). "Interestingly, the FUNDC1 expression level in LIHC is not related to tumor purity, suggesting that it is equally expressed in tumor cells and the tumor microenvironment." (PMID 31998650, 2019). "Moreover, after adjustment for tumor purity, FUNDC1 in LIHC had no relation to M1 macrophages but negatively correlated with ARG1+ M2 macrophages, while FUNDC1 in LUSC negatively correlated with ROS+ M1 macrophages and MRC1+ M2 macrophages." (PMID 31998650, 2019).
cardiovascular diseases (9 papers, 2021 to 2023). "FUN14 domain-containing protein 1 (FUNDC1), a novel mitophagy receptor, has been implicated in the pathogenesis of several diseases, including cardiovascular disease." (PMID 36815377, 2023). "The investigation of AMPK and FUNDC1 revealed evidence implicating AMPK/FUNDC1 in the pathophysiology of cardiovascular diseases." (PMID 37298100, 2023). "It is of great practical significance to elucidate the precise regulatory mechanism of FUNDC1 in the cardiovascular diseases at the molecular level." (PMID 35645834, 2022). "Here we review mitophagy mediated by FUNDC1 in mitochondria and its role in various forms of cardiovascular diseases." (PMID 35645834, 2022). "FUNDC1-mediated mitophagy could be a promising strategy to treat cardiovascular diseases, including HF." (PMID 35422895, 2022).
heart disease (6 papers, 2021 to 2024). "More directly, cardiac‐specific knockout of Fundc1 caused more severe cardiac dysfunction after MI, pointing out the important protective function of mitophagy in heart diseases." (PMID 35040256, 2022). "Recently, many studies have shown that FUN14 domain-containing protein 1 (FUNDC1) levels and phosphorylation status are highly associated with many diseases, including heart disease." (PMID 38828457, 2024). "FUNDC1 is a mitophagy receptor regulating chronic pathological progresses including heart diseases." (PMID 36470869, 2022). "FUNDC1 is a new type of mitochondrial receptor, which plays a protective role in heart disease." (PMID 34115550, 2021). "FUNDC1 was reported to be capable of relieving the symptoms of heart diseases." (PMID 34115550, 2021).
metabolic disease (6 papers, 2019 to 2022). A congenital disorder (due to inherited enzyme abnormality) or acquired (due to failure of a metabolically important organ) disorder resulting from an abnormal metabolic process. "FUNDC1‐related mitophagy dysfunction has been associated with many cardiovascular and metabolic diseases, as FUNDC1 has been identified to protect the cells from hypoxia‐associated damage." (PMID 33432610, 2021). "In cardiovascular and metabolic diseases, FUNDC1 is generally considered to be protective because FUNDC1-mediated mitophagy can alleviate damage caused by intracellular stress such as hypoxia and thus benefit overall outcomes." (PMID 31998650, 2019). "In cardiovascular and metabolic diseases, FUNDC1 is generally considered to play a protective role, since FUNDC1-mediated mitophagy can alleviate mitochondrial damage caused by intracellular stresses such as hypoxia and ischemia/reperfusion (I/R), thus benefiting cellular health overall." (PMID 35011599, 2021).
infection (2 papers, 2017 to 2020). The state of being infected such as from the introduction of a foreign agent such as serum, vaccine, antigenic substance or organism. "Four receptors (BNIP3L, Optineurin, FUNDC1, and TAX1BP1) were selectively modified upon Mtb infection; these modifications occurred in functional domains of these receptors and changed through the time course of infection." (PMID 31951200, 2020).
inflammation (1 paper, 2025). Aberrant reaction of the microcirculation characterized by movement of fluid and leukocytes from the blood into extravascular tissues. "Inhibition of Neutrophil Extracellular Traps (NETs) and enhancement of FUN14 Domain Containing 1 (FUNDC1)-dependent mitophagy attenuate microvascular endothelial ferroptosis in intestinal inflammation." (PMID 41326356, 2025).